PCDHA3 (protocadherin alpha 3)
Description:
Potential calcium-dependent cell-adhesion protein. May be involved in the establishment and maintenance of specific neuronal connections in the brain.
Synonyms: PCDH-ALPHA3
Tractability: Antibody: its Gene Ontology location is reachable by antibodies, with high confidence; UniProt places it where antibodies can reach, with medium confidence; UniProt predicts a signal peptide or a membrane-spanning region.
Gene: Protein-coding gene on chromosome 5 (140,801,028 to 141,012,347, forward strand). Ensembl gene ENSG00000255408.
Subcellular location: Cell membrane
Subcellular location (Human Protein Atlas): Golgi apparatus; Nucleoplasm
Gene Ontology:
Molecular function: cell adhesion molecule binding; calcium ion binding
Biological process: cell adhesion; nervous system development; homophilic cell-cell adhesion
Cellular component: plasma membrane; membrane
Genetic constraint (gnomAD): Loss-of-function variants: 41 observed, 65.42 expected, observed/expected ratio (o/e) 0.63, 90% interval 0.49 to 0.81. The upper end of that interval is the gene's LOEUF score, 0.81, which puts it in group 3 of 6, group 1 being the genes least tolerant of losing a copy. Missense variants: 1,304 observed, 1,315.5 expected, observed/expected ratio (o/e) 0.99, 90% interval 0.95 to 1.04. Synonymous variants: 640 observed, 587.9 expected, observed/expected ratio (o/e) 1.09, 90% interval 1.02 to 1.16.
Homologues: Orthologues: mouse Pcdha3 (85% identical), rat Pcdha3 (75% identical), pig PCDHA3 (67% identical). Paralogues in human: PCDHA4 (85% identical), PCDHA9 (83% identical), PCDHA2 (83% identical), PCDHA6 (83% identical), PCDHA7 (82% identical), PCDHA13 (82% identical), PCDHA8 (82% identical), PCDHA1 (82% identical), PCDHA5 (81% identical), PCDHA10 (81% identical), PCDHA11 (81% identical), PCDHA12 (79% identical), and 49 more.
Diseases named in the same sentence as PCDHA3 in open-access papers:
PCDHA3 is named in the same sentence as 12 diseases in open-access papers, as found by Europe PMC text mining. Sharing a sentence is not in itself a finding about the gene and the disease. The quoted sentences say what the papers report.
breast carcinoma (1 paper, 2022). "As an example of TET2 CD–mediated gene activation, a subset of TSS-CGIs from the breast cancer-methylated PDCHA locus selectively gained H3K4me3 in TET2 CD cells in correlation with the activation of the associated genes as shown for PCDHA4, PCDHA3, PCDHA9, and PCDHA10." (PMID 35351824, 2022).
endometrial cancer (1 paper, 2022). Primary or metastatic malignant neoplasm involving the endometrium (mucous membrane that lines the endometrial cavity). "In summary, ZXF1 regulates P21 expression in endometrial cancer through two mechanisms: by regulating P21 protein expression through the miR‐378a‐3p/PCDHA3 axis and by directly binding to P21 to prevent its CDC20‐mediated ubiquitin degradation." (PMID 33751805, 2022).
head and neck cancer (1 paper, 2023). A primary or metastatic malignant neoplasm affecting the head and neck. "The mutations in various genes, such as PCDHA3 and MAP3K19, altered the expression of C19orf80 in head and neck cancer patients." (PMID 37375208, 2023).
schizophrenia (1 paper, 2021). A major psychotic disorder characterized by abnormalities in the perception or expression of reality. "Subsequently, we tested the effects of HSV-1 infection on the expression of schizophrenia-associated protocadherins PCDHA2, PCDHA3 and PCDHA5 given their identification in cell adhesion biological processes in our earlier analysis." (PMID 34859219, 2021). "We found that schizophrenia-associated members of the clustered protocadherin family PCDHA2, PCDHA3 and PCDHA5 were downregulated by MIA and mapped to the cell adhesion biological processes." (PMID 34859219, 2021). "Additionally, we showed that schizophrenia-associated protocadherins PCDHA2, PCDHA3 and PCDHA5 were downregulated in a dose-dependent manner in neuronal precursor cells following HSV infection." (PMID 34859219, 2021).
squamous cell lung carcinoma (1 paper, 2023). A carcinoma arising from squamous bronchial epithelial cells. "The PCDHA3 gene inhibits epithelial–mesenchymal transition and the metastasis of squamous cell lung carcinoma." (PMID 37375208, 2023).
malignant tumors (1 paper, 2022). "This study is the first to explore the function of PCDHA3 in tumors and provides a new perspective for studying malignant tumors." (PMID 33751805, 2022).
tumor (1 paper, 2022). "Based on GEO and TCGA data, the expression of PCDHA3 in tumor tissues was lower than in normal control tissue." (PMID 33751805, 2022). "Although the colony formation capabilities of the two tumor cell lines were different, PCDHA3 overexpression suppressed colony formation in both cell lines." (PMID 33751805, 2022).
PCDHA3 also shares sentences with these, for which no sentence is quoted: bipolar affective disorder (1 paper); cervical cancer (1); endometrioid endometrial carcinoma (1); neurodevelopmental disorder (1); Usher syndrome type 1 (1).